SRXN1 (sulfiredoxin 1)
Diseases named in the same sentence as SRXN1 in open-access papers (continued):
Sharing a sentence is not in itself a finding about the gene and the disease.
female infertility (1 paper, 2025). Diminished or absent ability of a female to achieve conception. "Understanding the function of Srxn1 could pave the way for novel therapeutic strategies to treat disorders related to oxidative stress, such as female infertility associated with luteal phase defects." (PMID 40891754, 2025).
hepatitis B (1 paper, 2020). "Moreover, the SRXN1 overexpression brought HCC patients who infected with hepatitis B worse outcome in the training cohort, and the consistent phenomenon was observed in patients of the validation cohort." (PMID 32955798, 2020). "The 1‐year, 3‐year, and 5‐year AUC values showed SRXN1 had a good biomarker performance for HCC patients, especially in patients with poorly differentiated, advanced state or hepatitis B in the training cohort, and the results of the validated group confirmed the conclusion." (PMID 32955798, 2020).
Infertility (1 paper, 2020). "Interestingly, a decreased level of MSX1 in human and mouse endometrial tissue is linked to infertility, while SRXN1 contributes to oxidative stress resistance." (PMID 32232327, 2020).
liver fibrosis (1 paper, 2025). "In HSC-specific Srxn1-knockout mice (Srxn1ΔHSC), loss of Srxn1 enhanced HSC activation, increased protein sulfinylation and exacerbated liver fibrosis." (PMID 41131335, 2025). "Our group recently investigated the impact of protein sulfinylation and SRXN1 in liver fibrosis." (PMID 41131335, 2025). "The protective role of SRXN1 has been extensively investigated in preclinical models of ALI, ALD and hepatic fibrosis." (PMID 41131335, 2025).
pancreatic adenocarcinoma (1 paper, 2020). "SRXN1 expression is also associated with poor survival of patients with pancreatic adenocarcinoma." (PMID 32411320, 2020).
prostate tumor (1 paper, 2020). "The increase of SRXN1 protein expression was confirmed by immunohistochemistry in mouse prostate tumor paraffin samples." (PMID 32411320, 2020). "Database analysis of other studies from GEO profiles also showed increased expression of SRXN1 in LNCaP and PC-3, and in most prostate tumor cells." (PMID 32411320, 2020). "Analyses of human databases and prostate tissue microarrays demonstrated that SRXN1 is overexpressed in a subset of high-grade prostate tumors and correlates with aggressive PCa with worse prognosis and decreased survival." (PMID 32411320, 2020). "Quantitative PCR showed that prostate tumor cell lines LNCaP and PC-3 express higher levels of SRXN1 than the normal prostate cell line RWPE-1." (PMID 32411320, 2020). "To evaluate the pattern of SRXN1 protein expression in PCa, IHC analysis was performed, and we observed increased SRXN1 protein expression (higher intensity immunostaining) in prostate tumors compared to WT tissue." (PMID 32411320, 2020). "Thus, our cross-species analyses pinpoint SRXN1 as a potential therapeutic target for PCa, which plays an important role in protection of prostate tumor cells against oxidative stress." (PMID 32411320, 2020). "Among the prostate tumor cell lines, LNCaP has increased SRXN1 gene expression compared to PC-3." (PMID 32411320, 2020).
pulmonary disease (1 paper, 2021). "However, numerous studies reported that the anti-oxidative stress effect of SRXN1 could not protect against pulmonary disease." (PMID 35071014, 2021).
cancer (20 papers, 2016 to 2025). A tumor composed of atypical neoplastic, often pleomorphic cells that invade other tissues. "For instance, elevated levels of SRXN1 are associated with poor prognosis in several types of cancer, including non-small-cell lung cancer (NSCLC) and prostate cancer." (PMID 41333220, 2025). "Considering the pathogenic role of SRXN1 in human cancer, it has already been suggested as a new potential therapeutic target for different tumors, but not yet for PCa." (PMID 32411320, 2020). "Therefore, these inhibitors hold promises for overcoming resistance to existing cancer therapies, as SRXN1-mediated antioxidant defenses often underlie therapy resistance in tumors." (PMID 41131335, 2025). "SRXN1 has been reported to be associated with tumorigenesis by various cancers." (PMID 32746503, 2020). "In addition, SRXN1 has been implicated in cancer cell migration and invasion." (PMID 41131335, 2025). "The inhibition of SRXN1 amplifies intracellular ROS levels, leading to oxidative damage, mitochondrial dysfunction and apoptosis in cancer cells." (PMID 41131335, 2025). "Recent studies highlight J14 as a competitive SRXN1 inhibitor that selectively disrupts the redox balance in cancer cells." (PMID 41131335, 2025). "Results show that, while SRXN1 protects against liver damage, it also aids cancer cell survival in liver cancer." (PMID 41131335, 2025). "When NRF2 is overactivated, it boosts the levels of SRXN1, which lowers ROS and helps cancer cells endure oxidative stress, thereby supporting their growth and survival." (PMID 41333220, 2025). "As such, targeting SRXN1 with small-molecule inhibitors has emerged as a promising strategy to disrupt the antioxidant defenses of cancer cells and enhance ROS-induced cytotoxicity." (PMID 41131335, 2025). "Despite the exciting potential of J14 and LMT-328, challenges remain to ensure the selective targeting of SRXN1 in cancer cells while preserving redox homeostasis in normal tissues." (PMID 41131335, 2025). "Recent studies have shown that SRXN1 plays pivotal roles in the regulation of ferroptosis in some cancers." (PMID 36061193, 2022). "A receiver operating characteristic (ROC) curve analysis indicated the high diagnostic value of SRXN1 and KRT6A for smoking and cancer." (PMID 35071014, 2021). "Although these results collectively indicate that SRXN1 is critically involved in carcinogenesis and metastasis of various cancers." (PMID 32746503, 2020). "Researchers have already demonstrated that SRXN1 is essential for cancer cell proliferation, and its depletion decreases cell viability, suppresses cell migration, and inhibits tumor growth, increasing the aggressiveness of cancers with SRXN1 upregulation." (PMID 32411320, 2020). "The mRNA expression of SRXN1 in 24 types of cancers and normal tissues samples was visualized by the UALCAN website." (PMID 32955798, 2020). "Nrf2 and its target genes (e.g., heme oxygenase-1 (HO-1)], NAD(P)H:quinone oxidoreductase 1 (NQO-1), and sulfiredoxin-1 (Srx1)) protect not only normal cells but also cancer cells from oxidative stress." (PMID 26904167, 2016). "SRXN1 could promotes tumor growth and metastasis and correlates with worse prognosis and decreased survival in different carcinoma." (PMID 34906147, 2021). "Furthermore, elucidation of the roles of SRXN1 in tumorigenesis and metastasis of HCC would help to identify the roles of SRXN1 in other malignant cancers." (PMID 32746503, 2020). "SRXN1 was previously reported to regulate antioxidant responses in cancer cells." (PMID 32746503, 2020). "Patients with advanced PCa presenting SRXN1 overexpression may benefit from SRXN1 inhibition therapy, providing cancer patients with more personalized treatment." (PMID 32411320, 2020). "In addition to the overexpression of SRXN1 in PCa high-grade tumors, the current study also showed a close relationship between SRXN1 expression and both cancer aggressiveness and patient outcome." (PMID 32411320, 2020).
cancer (continued). "SRXN1 is also involved in cancer in a peroxiredoxin-dependent and independent manner." (PMID 32455559, 2020). "Thus, as an antioxidant protein, SRXN1 might undoubtedly contribute to the survival of cancer cells and play an important role in tumorigenesis." (PMID 32955798, 2020). "We identified that both SRXN1 and PRDX4 genes are upregulated in LUAD tumor tissue and correlated with the cancer development." (PMID 36829926, 2023). "While SRXN1 protects noncancerous cells in acute and chronic liver diseases, its overexpression in cancer cells, including HCC, promotes tumor survival, proliferation and resistance to oxidative stress-based therapies." (PMID 41131335, 2025). "SRXN1 plays a role in reducing oxidative stress by repairing peroxiredoxins, and its interaction with MMP3 may play a role in managing the oxidative environment within cancer cells." (PMID 40362252, 2025).
tumor (17 papers, 2006 to 2025). "The results depicted that SRXN1 level was significantly associated with tumor size (P = .006), TNM stage (P = .025), and BCLC stage (P < .001) in the training cohort." (PMID 32955798, 2020). "Moreover, higher SRXN1 levels were associated with worse survival outcomes and advanced clinicopathological features, including larger tumor size, higher tumor grade and increased metastasis." (PMID 41131335, 2025). "A clinical study involving 269 patients with HCC revealed significantly elevated SRXN1 expression in tumor tissues compared with adjacent normal liver tissues." (PMID 41131335, 2025). "In vivo studies using mouse subcutaneous xenograft and metastasis models further validated the tumor-promoting effect of SRXN1, demonstrating its ability to enhance both tumor growth and metastatic potential." (PMID 41131335, 2025). "Next, we examined one of the previously identified SRXN1 mRNA that constructs predictive model in several tumor cells." (PMID 38244584, 2024). "Our Western blot results show that the SRXN1 protein level was increased significantly in the tumor cell line." (PMID 38244584, 2024). "The result of the Quantitative reverse transcriptase-polymerase chain reaction (qRT-PCR) reveals SRXN1 mRNA levels were increased significantly in all tumor cell lines." (PMID 38244584, 2024). "This suppressive effect of SRXN1 or KRT6A knockdown on tumor growth was consistent with the results in vitro." (PMID 35071014, 2021). "In patients with NSCLC, SRXN1 and KRT6A expression was associated with the tumor–node–metastasis (TNM) stage, presence of metastasis, history of smoking and daily smoking consumption." (PMID 35071014, 2021). "In a series of experiments, we found that SRXN1 expression was up‐regulated in HCC tumour tissue samples and determined the correlation between SRXN1 expression and HCC patient survival." (PMID 32746503, 2020). "Immunohistochemical staining for Ki67 showed that SRXN1 knockdown suppressed the growth of cells in the tumour bulk." (PMID 32746503, 2020). "Prostate transcriptome data from Pb-Cre4; Ptenf/f mice comparing WT to tumor samples (PIN, MT, and AT) showed that the relative mRNA expression of Srxn1 increases progressively and significantly during tumor progression in all prostatic lobes, with p < 0.001." (PMID 32411320, 2020). "Both the mRNA and protein expression of SRXN1 were elevated in the tumour tissue compared with the peritumoral tissue." (PMID 32746503, 2020). "IHC staining of paraffin‐embedded HCC tissue samples also revealed more positive staining for SRXN1 in the tumour tissue than in the corresponding peritumoral tissue." (PMID 32746503, 2020). "We first examined the expression of SRXN1 in 102 pairs of previously collected human HCC tumour and peritumor tissue samples." (PMID 32746503, 2020). "All these studies suggest that when SRXN1 activity is inhibited, the high ROS levels exceed cell antioxidant capacity, resulting in accumulated damage that selectively leads to tumor cell death." (PMID 32411320, 2020). "Then the correlation between tumor SRXN1 level and clinicopathological characteristics was investigated." (PMID 32955798, 2020). "Consistent with our results, the SRXN1 mRNA levels reported in these databases were higher in tumour tissue samples than in their peritumoral counterparts." (PMID 32746503, 2020). "We aimed to investigate the expression of SRXN1 in HCC tumours and to elucidate how its aberrant expression modulates cellular signalling pathways in tumours." (PMID 32746503, 2020). "In vivo experiments showed SRXN1 promotes HCC tumour growth and metastasis in mouse subcutaneous xenograft and metastasis models." (PMID 32746503, 2020). "For example, the increased expression of SRXN1 (Sulfiredoxin 1) may be helpful in resisting oxidative stress produced by tumor cells." (PMID 38244584, 2024).
tumor (continued). "Additionally, SRXN1 expression was successfully knocked down in KD cells, as positive brown puncta were seldom observed in KD tumour tissue samples." (PMID 32746503, 2020). "In our study, we observed that decreasing SRXN1 mRNA in PCa cell line LNCaP decreased cell viability, reinforcing the importance of this antioxidant enzyme in PCa cells and suggesting that SRXN1 activity supports tumor cell survival and growth." (PMID 32411320, 2020). "Meanwhile, we observed the smoking-induced upregulation of SRXN1 and KRT6A expression in 75 matched tumor–normal tissue pairs from patients with NSCLC who were enrolled in our study." (PMID 35071014, 2021). "To verify the carcinogenic roles of SRXN1 and KRT6A in NSCLC, we measured the expression of these genes in 75 paired NSCLC and non-tumor tissues by RT-qPCR." (PMID 35071014, 2021). "Tumorigenicity assays in nude mice confirmed that the siRNA-mediated downregulation of SRXN1 and KRT6A expression inhibited tumor growth in vivo." (PMID 35071014, 2021). "SRXN1‐regulated ROS modulated p65, which inhibited BTG2 expression and ultimately led to migration and invasion by HCC cells, as well as tumour metastasis in vivo." (PMID 32746503, 2020). "Indeed, this tumor expressed six of the NRF2 targets (CES1, CYP4F1, GSTM3, ARK1C1/3/4, AKR1C2, SRXN1, and PTGR1) more than 16-fold above their respective mean expressions for the entire cohort and 24 proteins more than 4-fold above their means." (PMID 37716475, 2023). "Due to limited experimental conditions, we plan to knock out or knock down SRXN1 expression in PC3 and DU145 cells and verify whether tumour cell sensitivity to radiotherapy will be increased after inhibiting SRXN1 expression." (PMID 37726767, 2023). "In this study, we discovered that SRXN1 expression is up‐regulated in tumour tissue compared with adjacent nontumour tissue." (PMID 32746503, 2020). "Next, SRXN1 expression in different subgroups of HCC patients from TCGA database was further analyzed based on gender, age, ethnicity, individual HCC cancer stages, and tumor grade." (PMID 32955798, 2020). "Importantly, we identified BTG2 as a downstream target of SRXN1; This provides a novel layer of evidence for the tumour‐promoting function of SRXN1 and its regulatory network in HCC tumour metastasis." (PMID 32746503, 2020). "However, neither SRXN1 nor KRT6A expression was correlated significantly with age, sex or tumor size (P > 0.05)." (PMID 35071014, 2021).
neurodegenerative disease (2 papers, 2015). A disorder of the central nervous system characterized by gradual and progressive loss of neural tissue and neurologic function. "The findings of this study suggest that Srxn1 may be a novel target for neuroprotective intervention in neurodegenerative diseases." (PMID 25955519, 2015).
SRXN1 also shares sentences with these, for which no sentence is quoted: colorectal cancer (4 papers); infection (4); cardiovascular diseases (3); adenocarcinoma (2); Hypertension (2); liver cancer (2); alcoholic liver diseases (1); allergic disease (1); atherosclerosis (1); cerebrovascular disease (1); cognitive decline (1); colon carcinoma (1); dyslipidemia (1); esophageal cancer (1); heart failure (1); Hepatic steatosis (1); hippocampal atrophy (1); ischaemic heart diseases (1); lymph node metastasis (1); Obesity (1); osteoporosis (1); pancreatitis (1); prostatic intraepithelial neoplasia (1); proteinopathy (1); psychiatric disorder (1); type 2 diabetes (1).